TNF (tumor necrosis factor)
Diseases named in the same sentence as TNF in open-access papers (continued):
Sharing a sentence is not in itself a finding about the gene and the disease.
infection (continued). "Following the initial infection of the lungs by SARS-CoV-2, a cytokine storm is generated, characterized by the release of various cytokines such as tumor necrosis factor-alpha (TNFα), interleukin-1β (IL-1β), and IL-6." (PMID 38162133, 2023). "High levels of tumor necrosis factor (TNF), C-reactive protein (CRP), and interleukin 6 (IL-6) point to the involvement of infection and inflammation in the etiology of GDM." (PMID 36993820, 2023). "PSMB8 overexpression reduces the virus-induced activation of NF-κB promoters and suppresses the expression of proinflammatory IL-1β, TNF-α, IL6, IL8, and IFN-γ upon infection with nerve necrosis virus." (PMID 38031182, 2023). "Elevated expression of cardiac VEGF, Ang-1 and Ang-2, and reduced production of TNF and CCL5 were observed in the Y strain infection compared to the infection with the Colombian strain." (PMID 37998013, 2023). "Infection with this bacterium was shown to increase the production of IFN-γ, TNF-α, and chemokines such as CCL3, CCL4, CCL5, CCL11, and CXCL1." (PMID 38139161, 2023). "Mothers with ongoing infection exhibited higher levels of the antiviral mediator IFN-α2, the inflammatory cytokines IL-33 and TNF-α, the antiinflammatory cytokine IL-10, and the chemokine MCP-1." (PMID 37490342, 2023). "Outliers with elevated biomarkers observed in both pre-infection specimens included IL-1β (N=1 participant), suPAR (N=2), MCP-1/CCL2, sCD163, and CRP (N=3), TNFα (N=9) and/or leptin (N=23)." (PMID 37461626, 2023). "TRAIL is a type II transmembrane protein and belongs to the TNF/TNFR superfamily, which is involved in infection control and the regulation of both innate and adaptive immune responses." (PMID 37342494, 2023). "This study analyzes the efficacy of LL-37 cream in enhancing wound healing rate and decreasing the levels of IL-1α, TNF-α, and the number of aerobic bacteria colonization in DFU with mild infection." (PMID 37480520, 2023). "In contrast, pH1N1 infection induced the greatest AAV NP response and strong CD8 TNF production in TBLN and CD4 TNF in TBLN and PBMC." (PMID 37153548, 2023). "In a subset of matched infection-naïve cases and controls, vaccine breakthrough cases had lower CD4+ and CD8+ IFNγ and tumor necrosis factor (TNF) responses to Delta S peptides compared with controls." (PMID 37655880, 2023). "TNF-α, IL-6, IL-8, IL-10, IL-13, and IL-33 in children with HRSV were significantly increased in severe infections compared to mild infections." (PMID 37239461, 2023). "Compared to the control, the tumor necrosis factor-α (TNF-α) gene was firmly upregulated in gill tissue at all-time points, particularly at day 14 post-infection." (PMID 37337042, 2023). "Parallelly, in the infection of Plasmodium chabaudi, TLR7 is the primary Myd88-dependent sensor at 24 hours post infection, promoting IFN-α and IFN-β production and a cytokine response (IL-10, TNF, IL-12, and IFN-γ)." (PMID 37180169, 2023). "The levels of TNF-α in both primary astrocytes and BV2 cells infected with the two S. parasuis strains peaked at 12 h post-infection and gradually decreased thereafter." (PMID 37111486, 2023). "The MHC-I pathway-related genes (TNF, HSP70, TAP1/2, and TAPBP) were upregulated after infection in the head kidney and spleen compared to those of the MHC-II pathway." (PMID 36835242, 2023). "An array of cytokines, including Interleukins (IL), IL-12, IL-23, IL-6, IL-1, tumour-necrosis factor-alpha (TNF-α) and IFN-γ are released during infection and drive the immune response and containment of the infection." (PMID 38089636, 2023). "The clinical improvements and radiological findings were also consistent with decreased levels of cytokines, such as IL-6, IL-10, TNF-α, and IFN-γ, along with improvement of inflammation and infection markers." (PMID 37041589, 2023).
infection (continued). "In the present study, following infection with Salmonella Enteritidis, the levels of IL-1β, IFN-γ, TNF-α, and IL-6 rose dramatically, which is consistent with the findings of earlier research." (PMID 37990191, 2023). "Consistent with the murine infection model results, vimentin in STEC contributed to the transcription of IL-6, TNF-α, and IL-8." (PMID 36717839, 2023). "High concentrations of IFNɣ, TNFα, IL-10, IL-13, and MIP-1β were found during infection, as well as high concentrations of IL-7 and MCP-1 after recovery, in both the hospital ward and the ICU." (PMID 36975498, 2023). "We evaluated the systemic and tissue parasitism, the survival and the body mass rate, the release of inflammatory mediators (TNF, IL-6, IL-15, CCL2 and creatine kinase) and the tissue inflammation at day 30 post-infection." (PMID 37505639, 2023). "Such patients exhibit elevated levels of tumor necrosis factor (TNF)-α and Th1/Th2 cytokines; cytokine-induced cell damage is thought to aggravate infection." (PMID 37883347, 2023). "In the present study, we report that infection with BCG significantly induces macrophage apoptosis and induces the production of DUSP1, TNF-α and IL-1β." (PMID 36788275, 2023). "To assess the impact of B. pertussis internalization on our readout which is TNF secretion, we treated MPI with cytochalasin D, an inhibitor of actin polymerization and phagocytosis, prior to infection." (PMID 37841236, 2023). "Next, we analyzed the IFN type I-dependent ISG response after the infection of human synovial MSCs with a low MOI of ONNV, alone or in combination with TNF-alpha or IFN-γ." (PMID 37958918, 2023). "We analyzed the effect of PACAP pre-treatment on pro-inflammatory cytokines IL-1β, IL-6, TNF-α, and IFN-γ in RTS11 cells after challenge with Y. ruckeri at day 3 post-infection (day 4 after PACAP exposure)." (PMID 37887185, 2023). "Upon infection, macrophages are activated to induce the expression of type I IFN and proinflammatory cytokines such as IL-6 and TNF-α." (PMID 38005948, 2023). "As in HFFF-TERTs, infection of THP-1 macrophages also promoted downregulation of cIAP1 (BIRC2), a key regulator of the TNF-dependent extrinsic pathway of apoptosis." (PMID 38065956, 2023). "Infection with both ZIKV lineages was characterized by a more proinflammatory and chemotactic profile, mediated by high levels of IL-1β, IL-6, TNF-α, CCL-2, CCL-3, CCL-7, CXCL8, IP-10, and VEGF." (PMID 37227282, 2023). "One day following R7GeMC infection, cultures were washed to remove input virus and treated with the LRAs phorbol 12-myristate 13-acetate (PMA; 10 ng mL−1), tumor necrosis factor alpha (TNFα; 10 ng mL−1), or with DMSO as a vehicle control." (PMID 37676006, 2023). "Elevated expression of multiple inflammatory genes, including IL6, TNF, IL10, and IL1B, were observed in the CD163+MRC1+TREM2 Mac and CD163+MRC1− subsets in both Cohort 1 and 2 after infection." (PMID 37024448, 2023). "From 7 to 14 dpi, the HuN4 infection group exhibited higher levels of IL-1β, whereas the SD53-1603 infection group displayed higher levels of TNF-α and IFN-γ." (PMID 37920268, 2023). "The adaptive response characterized by T-helper 1 (Th1) activation produces cytokines such as interferon-gamma (IFN-γ), interleukin-2 (IL-2), and tumor necrosis factor-alpha (TNF-α), which help to control the infection." (PMID 37375511, 2023). "Both IL-12 and IL-15 are known activators of NK cells, which control infection through the secretion of perforin and granzyme B and production of IFN-γ and TNF-α." (PMID 37261350, 2023). "For half of the subjects who died, plasma levels of TNF-α and IFN-ɣ are low compared to subjects who survive infection." (PMID 37923927, 2023). "The levels of interleukin (IL)-6, IL-1β, and tumor necrosis factor α (TNF-α) after infection with ΔadcAΔlmb at 9 and 12 h were significantly lower than those after WT infection." (PMID 37212676, 2023).
infection (continued). "TNF-α and IFN-γ, which are proinflammatory cytokines, promote acute inflammation in the resistance response to infection." (PMID 36830548, 2023). "Consistent with IFN-γ ELISpot assay results, the frequencies of IFN-γ, TNF, and IL-2 single, double, and triple producers within the CD4+ and CD8β+ T-cell subsets were overall low after H3N2 single infection (mean < 0.5%)." (PMID 37287962, 2023). "This leads to the release of cytokines such as IL-6, IL-8 and tumor necrotic factor-alpha (TNF-α), which are part of the innate immune response that helps eradicate the infection." (PMID 38098676, 2023). "At 3 d post-infection, the cytokines interferon gamma (IFN-γ), IL-6, MCP-1, and TNF-α were significantly reduced in TgΔLOXL1-infected mice, which prompted us to examine TgΔLOXL1 in IFN-γ KO mice." (PMID 37646522, 2023). "The naïve infection control group showed the highest levels of IFN-γ, TNF-α, IL-6, and IL-1β cytokines in lung samples at 6 days after infection." (PMID 37515025, 2023). "We found that TgCtwh3 infection led to hippocampal damage, producing large amounts of pro-inflammatory cytokines, including IFN-γ and TNF-α." (PMID 37651502, 2023). "Infection of BMDCs with EBs opsonized with male IgG enhanced expression of chemokines CXCL1, CXCL2, CXCL5 and pro‐inflammatory cytokines TNF, IL1β and IFNγ compared to uninfected or non‐opsonized controls." (PMID 38441219, 2023). "The levels of IL-12p70, MCP-1, IL-10, IL-1β, IFN-γ, IL-2, M-CSF, VEGF, ICAM-1, and P-selectin increased after infection; however, the expression of all except MCP-1, IFN-γ, and P-selectin was strongly suppressed by anti-TNF-α Ab treatment." (PMID 37939119, 2023). "Inflammatory cytokines, such as IL-1, IL-6, TNF-α, and IFN-γ, are the main mediators of immunological and pathological responses to stress and infection." (PMID 37756067, 2023). "This was evidenced by significant, or close to significant, interactions between diet and infection for the expression of CXCL9, CXCL10, and TNF, indicating that infection-induced changes in gene expression were attenuated by inclusion of dietary Fer-SL." (PMID 38081984, 2023). "Th1 cells mainly respond to the infection of intracellular pathogens, including intracellular parasitic bacteria and viruses, by secreting IFN-γ, IL-2, and TNF-α." (PMID 37357919, 2023). "First, on day 14, after three immunizations, we intraperitoneally injected each group of mice with 2.81 × 107 CFU B abortus A19 per mouse to detect the changes in cytokines (TNF-α, IFN-γ, IL-12) after infection." (PMID 36911199, 2023). "Inflammatory mediators including IL1β, TNF, and IL6 displayed significant differential secretion across the time points, indicating their contribution to a pro-inflammatory reaction to infection." (PMID 37333188, 2023). "There was a significant increase in in the secretion of cytokines IL-2, IL-6, IL-10, TNF-α, and IFN-γ in the H3N2 virus-infected group 24 hours after infection." (PMID 37900310, 2023). "We showed that BMDCs from an early stage of AE infection expressed high levels of IL-6 and TGF-β, while IL-10 and TNF-α gene expression levels were persistently low in concordance with previous reports." (PMID 37888588, 2023). "Concentrations of IFN alpha and IL-8 increased gradually over the course of infection, whereas levels of IFN gamma, IL-2 and TNF alpha were relatively stable until day 9 post-infection at which point dramatic increases were observed." (PMID 36992478, 2023). "TNF- α is an important pro-inflammatory cytokine in the TNF family, which can clear the infection by activating immune cells and promoting the secretion of other cytokines." (PMID 37647293, 2023). "Of note, the infection of Caco-2 cells with K. pneumoniae NTUH-K2044 strain induced levels of MCP-1, IL-8, IL-6, and TNF-α that were similar to those found in cells stimulated with LPS." (PMID 37240146, 2023).
infection (continued). "Within splenocytes, expression of IFNγ, TNFα, IL17, IL13, IL10, and TGFβ were changed by both infection and vaccination within CD4 and CD8 T cells and regulatory T cells." (PMID 36799886, 2023). "Expression of viral latent proteins after infection amplified the viral effects on p38 and MK2, but also on ZFP36L1, altogether resulting in a transitory and limited increase in IL-6 and TNFα transcription and release." (PMID 37830871, 2023). "In mice, R7 more effectively protected mice from infection with MDR E. coli or LPS and alleviated inflammation than its parental peptides by inhibiting the production of proinflammatory cytokines (TNF-α, IL-6, and IL-1β) and promoting IAP and IL-10." (PMID 37973936, 2023). "Bacterial colonization and infection elicit an inflammatory reaction such as HCA, and increased levels of neutrophil infiltration, IL-6 and TNF-α, which are some of the classic signs of amniotic infection and inflammation." (PMID 37600782, 2023). "Following secretion of chemokines and cytokines such as IL-1β, IL-6, TNF-α, IL-21, and IL-8, the SARS-CoV-2-induced cytokine storm and hyperinflammatory response have pivotal roles in infection severity, AKI development, and death." (PMID 37026010, 2023). "The recruitment of MDMs correlated with increased TNF-α levels in the BALF, and PpargΔM mice showed greater levels after cadmium and infection than Ppargfl/fl mice." (PMID 36928191, 2023). "Particularly, a significant difference was observed for TNF‐α, IL‐8, and MCP‐1 four h post‐infection, and of IL‐6, IL‐8, and MCP‐1 24 h post‐infection in U937 macrophages and hGFBs, respectively." (PMID 35964247, 2023). "Furthermore, infection with some viruses (e.g., human T-cell leukemia virus type 1 [HTLV-1]) causes increased levels of GSK3β phosphorylation and decreased levels of proinflammatory cytokines tumor necrosis factor alpha (TNF-α), IL-8, and monocyte chemotactic protein 1 (MCP-1)." (PMID 36995259, 2023). "In particular, HBV-specific CD8+ T cells are the main effectors of viral clearance in cases of infection resulting in healing through killing of infected hepatocytes and production of antiviral cytokines (interferon-γ, IFN-γ and tumor necrosis factor, TNF)." (PMID 37108816, 2023). "The cell model and mouse model infection experiments indicated that TF1 decreased the adhesion ability and virulence of SC19, and reduced the production of IL-6, and TNF-α in infected mice." (PMID 37108608, 2023). "Bacterial toxins are crucial in the induction of the synthesis of this protein, which is also stimulated by high levels of tumor necrosis factor (TNF-α) and interleukin-6 (IL-6), produced in response to infection." (PMID 37762882, 2023). "Our findings revealed that inflammatory cytokines, including TNF-α and IL-6, Th1-related cytokine IFN-γ, and Th2-related cytokine IL-5 were significantly elevated in HD patients after breakthrough infection compared to after booster immunization." (PMID 37515030, 2023). "Throughout the infection and treatment period, we measured the levels of Interleukin-12 subunit alpha (IL-12), Interferon-gamma (IFN-γ), TNF, Tumor growth factor (TGF), and T lymphocytes using ELISA." (PMID 38036985, 2023). "After infection of THP-1 with BCG (MOI = 10) for various time intervals, TNF-α and IL-1β transcripts were significantly upregulated in a time-dependent manner." (PMID 36788275, 2023). "The infection with Mtb increased the production of IL-1β, IL-1α, IL-12, Interferon γ (IFN-γ), TNF, and the Granulocyte macrophage colony stimulating factor (GM-CSF)." (PMID 37375056, 2023). "The HLA-A11/DR1 mice strain induced lower levels of several cytokines (IL-2, IL-10, IL-18, IL-1β, TNF-α, IL-1α, IL-28, and ENA78), but showed increased secretion of IFN-γ, RANTES, IP10, and Eotaxin at 12 h post-infection, compared to the WT group." (PMID 38035330, 2023).
infection (continued). "In contrast to ST4 colonized mice, infection with ST7 markedly increased the percentage of pro-inflammatory cytokines IL-17A and TNF-α-producing T cells in the colonic lamina propria (LP)." (PMID 36793854, 2023). "Taken together, the downregulated TNF-α and IL-1β secretion by PRRSV in immune and PGE cells reflects a poor innate immune response which leads to secondary infection by other microbial pathogens." (PMID 37099541, 2023). "Different to the previous studies addressing PRRSV vaccination/ infection and DON, we also analyzed T-cell responses by IFN-γ ELISpots and ICS for TNF-α and IFN-γ." (PMID 36781434, 2023). "As depicted in, TNF-α, IL-6, IL-8, IL-10, IL-13, and IL-33 in children with HRSV were significantly increased in severe infection compared to mild infection (p < 0.05)." (PMID 37239461, 2023). "Eventually, the inflammation caused by the release of Interleukins 1–6-32–34, TNF alpha, etc., and activation of multiple intracellular pathways (through CD-147 and NLRP3 inflammasome, etc.), may lead to rapid unstable plaque formation even after resolution of the infection." (PMID 36829118, 2023). "At 3 d post-infection, all the cytokine levels of IL-6, MCP-1, TNF-α, and IFN-γ in ΔTgLOXL1-infected mice were lower compared to the cytokine level in parental-infected mice." (PMID 37646522, 2023). "Following infection of PAMs with ASFVΔI10L, ASFVΔH240R, or ASFVWT at a multiplication of infection (MOI) of one for 48 hours, the PAMs were treated with TNF-α or RPMI-1640 medium for another 20 minutes." (PMID 37607059, 2023). "The level of transcription factor occupancy of the promoter region of TNF-α and IL-1β in T. marneffei-infected NCOR2-013 overexpressing macrophages at 24 h post-infection were detected." (PMID 37845378, 2023). "The infection induced an enduring high inflammatory cytokine response in HLA-A11/DR1 mice after 72 h, including elevated TNF-α, IL-6, IFN-γ, and GRO-α levels compared to the WT mice." (PMID 38035330, 2023). "To investigate the functionality of spike-specific CD4+ T cells after natural infection and subsequent vaccination, we measured the intracellular production of IFN-γ, IL-2, and tumor necrosis factor (TNF) in response to peptide stimulation." (PMID 38064569, 2023). "In analyzes of lung homogenates 3 days post infection, BALB/c mice had higher protein levels of IP-10, IL-1β, TNF-α, M-CSF, IL-4, IL-12, IL-15 and IL-17." (PMID 36810092, 2023). "Increased expression of TNF-α, IL-1β, and IL-6 was seen predominantly with DENV2 infection and at higher levels with Mon601 compared with DENV1 and DENV2 field isolates." (PMID 37515098, 2023). "A distinct intestinal cytokine profile was found in mice treated with canine LAB, which was characterized by higher levels of IFN-γ and IL-10, and lower concentrations of TNF-α, KC and MCP-1 than controls, in both infection models." (PMID 38076565, 2023). "In further analysis of infection-naïve individuals by ICS, lower CD4+ and CD8+ IFNγ and TNF responses to Delta S peptide pools were found among cases compared to controls." (PMID 37655880, 2023). "Activated Vγ9Vδ2 cells can infiltrate the brain parenchyma in response to infection and are thus potent producers of immunostimulatory cytokines such as interferon-γ (IFN-γ) and tumor necrosis factor-α (TNF-α)." (PMID 38136330, 2023). "During the acute phase of infection, more than 80% of pDCs in the intestinal mucosa were produced by CD4+, and the responses of IFN‐α and TNF‐α, as well as TLR7/8 activation, were considerably higher than in naïve mice." (PMID 37773693, 2023). "Many of them are related to a state of immunosuppression, most notably infection with the human immunodeficiency virus (HIV), malignancies, and ongoing immunosuppressive therapy, particularly with tumor necrosis factor-alpha (TNF-α) blockers." (PMID 37575717, 2023).